FOXP2 (forkhead box P2)
Diseases named in the same sentence as FOXP2 in open-access papers (continued):
Sharing a sentence is not in itself a finding about the gene and the disease.
schizophrenia (36 papers, 2009 to 2025). A major psychotic disorder characterized by abnormalities in the perception or expression of reality. "A recent study reported that a polygenic risk score obtained from FOXP2 genetic clusters correlated with functional connectivity in the inferior frontal gyrus in first-episode schizophrenia patients with short illness duration." (PMID 36371445, 2022). "FOXP2, cognitive deficits, and schizophrenia are associated with neurodegenerative pathophyisiology." (PMID 35992594, 2022). "(2011) identified an association between the FOXP2 rs2396753 and gray matter (GM) concentration changes in schizophrenia patients." (PMID 32734433, 2021). "Recently, a common FOXP2 SNP was nominally associated with phonemic verbal fluency in the Western Australian Family Study of Schizophrenia." (PMID 32734433, 2021). "FOXP2 has been implicated in attention deficit-hyperactivity disorder, schizophrenia, and multisite chronic pain." (PMID 34603368, 2021). "What further complicated things was that some genes were linked to both disorders; for example, CNTNAP2 (itself a FOXP2 target) was one of those genes (it was also linked to schizophrenia)." (PMID 34773992, 2021). "Some studies implicated FOXP2 either in either schizophrenia itself or in language ability in schizophrenia patients, whereas other studies found no such associations." (PMID 34773992, 2021). "A recent study identified FOXP2 as susceptible loci for schizophrenia using genome-wide association method." (PMID 31425145, 2019). "FOXP2 is located on chromosome 7q31 which has been identified as the susceptible locus for schizophrenia through genome-wide association studies." (PMID 31425145, 2019). "Recently, the FOXP2 polymorphism rs10447760, located in the 5′regulatory region was found to correlated with schizophrenia." (PMID 31425145, 2019). "SHEsis software was used to investigate the association of FOXP2 rs10447760 with schizophrenia, followed by logistic regression." (PMID 31425145, 2019). "The forkhead-box P2 (FOXP2), involving in language and memory function, has been identified as susceptibility to schizophrenia." (PMID 31425145, 2019). "The same research group demonstrated that FOXP2 polymorphism rs10447760 was strongly correlated with susceptibility of schizophrenia in Chinese Han population." (PMID 31425145, 2019). "In accordance with a neurogenic role of FOXP2 in neuropathogenetic processes, one polymorphic variant of FOXP2, rs2396753, is associated with hallucinations in schizophrenia and correlated with grey matter reduction." (PMID 29725501, 2018). "Genes that mediate linguistic behavior are associated with schizophrenia; a polymorphism in the FOXP2 gene for instance associates with schizophrenia, with poverty of speech, and possibly with auditory verbal hallucinations." (PMID 28239361, 2017). "Here, we set up to evaluate NAP, as a treatment against cognitive deficits and impairments in Foxp2 expression in a DISC1 mutated mouse model for schizophrenia." (PMID 26553741, 2015). "Interestingly, this association was only found in male patients with schizophrenia who also carried the FOXP2 rs10447760 CC genotype (ß = 0.63, t = 3.44, p = 0.001)." (PMID 35992594, 2022). "FOXP2 plays a critical role in the neuronal processes that contribute to language and speech performance, and its polymorphisms have been reported to be involved in the pathophysiology of cognitive function and language phenotypes in schizophrenia." (PMID 35992594, 2022). "Furthermore, our results suggest that the FOXP2 rs2396753 affects mRNA levels, thus providing new knowledge about its significance as a potential susceptibility polymorphism in schizophrenia." (PMID 32734433, 2021). "Whatever the cause, the lower expression of FOXP2 in heterozygous schizophrenia patients than heterozygous controls could explain the reduced expression of this gene that we found in PFC of schizophrenia patients." (PMID 32734433, 2021).
schizophrenia (continued). "The underlying molecular mechanism by which FOXP2 may be implicated in the decrease in GM density in schizophrenia patients is unknown and merits further research." (PMID 32734433, 2021). "Here we evaluated the potential impact of the common FOXP2 rs2396753 polymorphism in schizophrenia." (PMID 32734433, 2021). "Here, we evaluated whether common polymorphisms of FOXP2 influence brain structure in schizophrenia." (PMID 32734433, 2021). "Interestingly, our results showed significant association between FOXP2 rs10447760 and cognitive performance in schizophrenia." (PMID 31425145, 2019). "Moreover, SNPs of the FOXP2 gene were identified to be associated with schizophrenia and major depression within the Chinese population." (PMID 26553741, 2015). "Importantly, FOXP2 is associated with the ability to acquire spoken language in humans, while language deficit is considered one of the symptoms of schizophrenia." (PMID 26553741, 2015). "Therefore, it is reasonable to look for risk alleles to schizophrenia vulnerability in FOXP2, a gene for which an implication in the development of language is well accepted." (PMID 20649982, 2010). "FOXP2 is a transcription factor important for some neuronal functions including reflex, development of cerebellum, developmental disorders, and is implicated in schizophrenia." (PMID 20436668, 2010). "In this work, we also analyzed whether the polyQ stretches at exons 5 and 6 of FOXP2 are polymorphic and if so, determine its potential association with schizophrenia vulnerability." (PMID 20649982, 2010). "Furthermore, FOXP2 has been associated with schizophrenia in genome-wide association studies." (PMID 35992594, 2022). "In a preliminary study, we found that the common FOXP2 rs2396753 single nucleotide polymorphism (SNP) might be involved in language disorder vulnerability, including thought disorders and auditory hallucinations in schizophrenia." (PMID 32734433, 2021). "Identification of the transcriptional targets of FOXP2 revealed that this protein could regulate genes involved in development and function of the brain, genes under positive selection in human lineage and genes associated to schizophrenia." (PMID 20649982, 2010). "FOXP2 expression was reduced in the prefrontal cortex of male schizophrenia patients, and we observed increased FOXP2 expression in schizophrenia, particularly in the midbrain ependymal cells." (PMID 36192459, 2022). "Collectively, this evidence suggests that FOXP2 contributes to both cognitive deficits and obesity in patients with schizophrenia." (PMID 35992594, 2022). "BMI was positively associated with language scores in male patients with schizophrenia (ß = 0.60, t = 3.30, p = 0.001), as well as in patients with schizophrenia who carried the FOXP2 rs10447760 CC genotype (ß = 0.53, t = 3.16, p = 0.002)." (PMID 35992594, 2022). "Our study reveals a sex difference in the language deficits of schizophrenia patients and shows sexual dimorphism in the contribution of FOXP2, BMI, and their interaction to cognitive deficits in patients with schizophrenia." (PMID 35992594, 2022). "Ependymal nuclei exhibited the largest number of DEGs, including reduced PDE4D and increased FOXP2 expression in schizophrenia." (PMID 36192459, 2022). "Other genes in this FOXP2 gene cluster include NRG3, ERBB4, DLX1, ROBO2, and ROBO2, all are susceptibility gene in schizophrenia and is related to development." (PMID 33658499, 2021).
schizophrenia (continued). "Collectively, all these findings suggest that common polymorphisms of FOXP2 may be involved in language related phenotypes in the general population and thereby may contribute to psychopathology and language impairment in neuropsychiatric disorders as schizophrenia." (PMID 32734433, 2021). "As far as we know, this is the first study that combined structural MRI and brain gene expression analysis to search for the role of FOXP2 in the schizophrenia vulnerability." (PMID 32734433, 2021). "For example, EA interacts with the forkhead box P2 gene, involved in the development of speech and language, with respect to auditory verbal hallucinations in schizophrenia." (PMID 33897484, 2021). "The involvement of FOXP2 in schizophrenia vulnerability was further confirmed in a large sample of the Chinese Han population." (PMID 32734433, 2021). "This study shows the importance of independent replication of neuroimaging genetic studies of FOXP2 as a candidate gene in schizophrenia." (PMID 32734433, 2021). "The model of covariance (ANCOVA) and multivariate analysis were conducted to investigate the effect of FOXP2 rs10447760 on cognitive impairment in schizophrenia." (PMID 31425145, 2019). "Other disorders found to involve MCP-related genes include schizophrenia (FOXP2 and GABRB2), intellectual disability and epilepsy (GABRB2), and neuroleptic-induced tardive dyskinesia (GABRB2)." (PMID 31194737, 2019). "Real-time PCR RNA expression analysis revealed a significant increase in Foxp2 transcripts in the hippocampus of the DISC1 schizophrenia mouse model, compared to the control group WT mice." (PMID 26553741, 2015). "In any case, our results relate the FOXP2 gene to one of the characteristic symptoms of schizophrenia, deficits in the language domain." (PMID 20649982, 2010). "In this study we investigated the role of FOXP2, a positively selected gene, in schizophrenia vulnerability." (PMID 20649982, 2010). "Twenty-seven SNPs of FOXP2 were genotyped in a cohort of 293 patients with schizophrenia and 340 controls." (PMID 20649982, 2010). "Emerging evidence suggests that FOXP2 may influence metabolic processes related to obesity by increasing BMI, particularly in individuals with neuropsychiatric conditions such as schizophrenia." (PMID 41082226, 2025). "Interestingly, a recent study indicated sexual dimorphism in the relationship between FOXP2 and body-mass index with cognitive deficits in schizophrenia." (PMID 37845254, 2023). "Genetic variation in both genes, FOXP2 and PDE4D, was previously associated with schizophrenia." (PMID 36192459, 2022). "Verbal fluency deficits and disorganized speech are often observed in schizophrenia patients, and may be related to altered FOXP2 expression and/or functioning." (PMID 36192459, 2022). "Mounting evidence suggests that body mass index (BMI) and FOXP2 may contribute to cognitive deficits in schizophrenia." (PMID 35992594, 2022). "These contrasting results might be explained due to cell type-specific effects of schizophrenia on FOXP2 expression activity, which are only evidenced through single-cell analysis." (PMID 36192459, 2022). "This suggests that BMI might affect cognitive deficits in schizophrenia as a condition of specific FOXP2 genotypes." (PMID 35992594, 2022). "This list also contains the FOXP1 and FOXP2 genes, which are required for development of speech and language in humans and interact with CNTNAP2, a member of the 47-gene list which is in the neurexin family of genes having known association with schizophrenia." (PMID 36711134, 2022). "A polygenic cluster related to language as well as schizophrenia, comprised of FOXP2, and NRG-ERBB signaling pathways, influences the connectivity of Broca’s area, which in turn influences the clinical expression of core symptoms in untreated early stages of schizophrenia." (PMID 33658499, 2021).
schizophrenia (continued). "Other authors studying a sample of this population suggested that FOXP2 might play a role in enhancing the vulnerability to psychotic symptoms in schizophrenia." (PMID 32734433, 2021). "FOXP2 expression was reduced in the PFC of the schizophrenia patients (p = 0.0121)." (PMID 32734433, 2021). "Several studies have related the FOXP2 rs2396753 with schizophrenia." (PMID 32734433, 2021). "The most recent meta-analysis indicated that FOXP2 rs10447760 significantly correlated with susceptibility schizophrenia in Caucasians, but not in Chinese Han population." (PMID 31425145, 2019). "Furthermore, our recent study demonstrated significant correlation between FOXP2 rs10447760 and the symptoms of chronic patients with schizophrenia in a Chinese Han population." (PMID 31425145, 2019). "Recently, computational evidence has been proposed for an auto-repression of FOXP2 by miR-3666 in cell lines, and uncovered a set of several hundred genes conjointly targeted by both, with a bias toward genes putatively involved in schizophrenia and/or autism spectrum disorder." (PMID 29725501, 2018). "Interestingly, FOXP2, a candidate gene for schizophrenia, interacts with NKX2-1 in the human lung, and is co-expressed with Nkx2-1 in the posterodorsal medial amygdala nucleus in mice." (PMID 27064909, 2016). "Our results are consistent with the human research, suggesting that FOXP2 may have an important role in schizophrenia." (PMID 26553741, 2015). "Whether the identification of DISC1 as a FOXP2 target places FOXP2 in schizophrenia-related pathways remains unclear." (PMID 22736078, 2012). "Epigenetic mechanisms affecting the expression of FOXP2 might contribute to the development of schizophrenia and related neurodevelopmental disorders." (PMID 20649982, 2010). "We hypothesized that FOXP2 could be considered a candidate gene that may confer vulnerability to schizophrenia or to the language related symptoms of this disorder." (PMID 20649982, 2010). "Furthermore, sexual dimorphism and FOXP2 rs10447760 may impact the influence of BMI on language-based cognitive deficits in schizophrenia patients." (PMID 35992594, 2022). "Thus, FOXP2 rs10447760 may be involved in pathophysiological mechanisms for cognitive impairments in schizophrenia." (PMID 31425145, 2019). "In summary, we found that FOXP2 polymorphism rs10447760 may not be involved in the susceptibility to schizophrenia, but may contribute to cognitive performance, especially immediate memory in schizophrenia." (PMID 31425145, 2019). "Our results further suggest that a combination of NAP with a standard of care RIS treatment can normalize FOXP2 altered expression, thereby protecting against brain dysfunction-related language disturbances which are associated with the negative symptoms of schizophrenia." (PMID 26553741, 2015). "Consequently, the FOXP2 gene might be involved in the language disturbances found in patients with schizophrenia." (PMID 26553741, 2015). "Thus, the FOXP2 gene might be involved in the language disturbances found in patients with schizophrenia." (PMID 26553741, 2015). "Intriguingly, three thalamic regions primarily shown to suffer reductions in volume in schizophrenia patients, the MD, pulvinar and CM all highly expressed both CNTNAP2 and FOXP2." (PMID 39990522, 2025). "The ependymal cluster exhibited the largest number of DEGs between schizophrenia and controls, including reduced PDE4D, and increased FOXP2 and EML6 expression activity in schizophrenia." (PMID 36192459, 2022). "Indeed, FOXP2 appears among the twenty-three clinically relevant genes common to ASD, bipolar disorder and schizophrenia." (PMID 29725501, 2018). "Our results do not support the involvement of FOXP2 in the vulnerability to schizophrenia as a global syndrome." (PMID 20649982, 2010). "However, the sex difference in the contribution of FOXP2 and BMI, as well as their potential interaction with cognitive deficits in schizophrenia, have not been investigated." (PMID 35992594, 2022).
schizophrenia (continued). "For instance hyper- DNA methylation of RELN, SOX10 [SRY (sex determining region Y)-box 10], FOXP2 (forkhead box P2), and HTR2A as well as hypo- DNA methylation of MB-COMT (membrane-bound catechol-O-methyltransferase) and HTR2A have been reported in schizophrenia." (PMID 25206360, 2014). "On the other hand, although the results are not conclusive, this is the first epigenetic study of FOXP2 in schizophrenia, opening a new way in which this gene could be related to this disorder." (PMID 20649982, 2010). "However, no study examined the role of FOXP2 on cognitive impairment in schizophrenia." (PMID 31425145, 2019).